PPBPP1 (pro-platelet basic protein pseudogene 1)
Synonyms: TGB2; formerly PPBPL1
Gene: Transcribed unprocessed pseudogene on chromosome 4 (73,847,866 to 73,848,829, forward strand). Ensembl gene ENSG00000250550.
Diseases named in the same sentence as PPBPP1 in open-access papers:
PPBPP1 is named in the same sentence as 3 diseases in open-access papers, as found by Europe PMC text mining. Sharing a sentence is not in itself a finding about the gene and the disease.
PPBPP1 shares sentences with these, for which no sentence is quoted: infection (3 papers); viral infection (3); tumor (1).